FABP3 (fatty acid binding protein 3)
Description:
FABPs are thought to play a role in the intracellular transport of long-chain fatty acids and their acyl-CoA esters.
Synonyms: H-FABP; MDGI; M-FABP; FABP11; O-FABP
Tractability: Small molecule: a structure with a bound ligand is known; a high-quality ligand is known; it has a high-quality binding pocket. PROTAC: its protein half-life has been measured; a small molecule that binds it is known.
Target class: Fatty acid binding protein family; Auxiliary transport protein
Gene: Protein-coding gene on chromosome 1 (31,364,010 to 31,376,850, reverse strand). Ensembl gene ENSG00000121769.
Subcellular location: Cytoplasm
Subcellular location (Human Protein Atlas): Focal adhesion sites; Golgi apparatus; Plasma membrane
Pathways (Reactome):
Metabolism: Triglyceride catabolism
Gene Ontology:
Molecular function: cytoskeletal protein binding; long-chain fatty acid binding; oleic acid binding; protein binding; lipid transporter activity; fatty acid binding; icosatetraenoic acid binding; lipid binding; long-chain fatty acid transmembrane transporter activity
Biological process: cholesterol homeostasis; intracellular lipid transport; long-chain fatty acid transport; negative regulation of cell population proliferation; phospholipid homeostasis; positive regulation of long-chain fatty acid import into cell; positive regulation of phospholipid biosynthetic process; regulation of fatty acid oxidation; triglyceride catabolic process; fatty acid metabolic process; response to fatty acid; response to insulin; response to xenobiotic stimulus
Cellular component: extracellular exosome; extracellular region; cytosol; nucleus; cytoplasm; sarcoplasm
Genetic constraint (gnomAD): Loss-of-function variants: 8 observed, 14.03 expected, observed/expected ratio (o/e) 0.57, 90% interval 0.33 to 1.03. The upper end of that interval is the gene's LOEUF score, 1.03, which puts it in group 4 of 6, group 1 being the genes least tolerant of losing a copy. Missense variants: 135 observed, 173.44 expected, observed/expected ratio (o/e) 0.78, 90% interval 0.68 to 0.9. Synonymous variants: 64 observed, 64.05 expected, observed/expected ratio (o/e) 1, 90% interval 0.82 to 1.23.
Homologues: Orthologues: chimpanzee FABP3 (100% identical), macaque FABP3 (97% identical), rabbit FABP3 (92% identical), pig FABP3 (90% identical), guinea pig FABP3 (89% identical), rat Fabp3 (89% identical), mouse Fabp3 (86% identical), dog FABP3 (80% identical), zebrafish fabp3 (73% identical), tropical clawed frog fabp3 (56% identical), Drosophila melanogaster fabp (47% identical), Caenorhabditis elegans lbp-7 (41% identical), and 1 more. Paralogues in human: FABP7 (66% identical), FABP4 (64% identical), PMP2 (62% identical), FABP9 (55% identical), FABP12 (51% identical), FABP5 (50% identical), CRABP2 (41% identical), RBP2 (41% identical), CRABP1 (40% identical), RBP7 (38% identical), RBP1 (34% identical), RBP5 (34% identical), and 3 more.
Diseases named in the same sentence as FABP3 in open-access papers:
FABP3 is named in the same sentence as 205 diseases in open-access papers, as found by Europe PMC text mining. Sharing a sentence is not in itself a finding about the gene and the disease. The quoted sentences say what the papers report.
myocardial infarction (68 papers, 2008 to 2025). Gross necrosis of the myocardium, as a result of interruption of the blood supply to the area, as in coronary thrombosis. "FABP1 has been suggested as a marker of renal failure, FABP3 as a marker of myocardial infarction, and FABP5 has lately been debated as a diagnostic marker for Sjögren’s syndrome." (PMID 32272779, 2020). "Pathologically elevated FABP3 expression promotes cardiomyocyte apoptosis in myocardial infarct zones and border regions, worsening cardiac dysfunction through impaired left ventricular ejection fraction." (PMID 41150529, 2025). "Researchers have suggested the potential of FABP‐3 as a biomarker for CVDs, including heart failure and myocardial infarction." (PMID 38269633, 2024). "For their unique cardiac-expression profile, FABP3 has been proposed as an effective biomarker of myocardial injury as FABP3 is readily released from heart muscles into the blood following a heart attack." (PMID 36681124, 2023). "Recently, H-FABP (FABP3) has emerged as another potentially promising biomarker for myocardial injury because it increases as early as 0–3 h from the onset of acute myocardial infarction." (PMID 37740216, 2023). "The release of FABP3 from the injured myocardium has been observed in both animal models and myocardial infarction patients." (PMID 36681124, 2023). "FABP3 has been demonstrated to be a biomarker for heart injury, particularly myocardial infarction (MI)." (PMID 36140383, 2022). "Under pathological conditions, elevated FABP3 expression level promotes embryonic cancer cell apoptosis and cardiomyocyte apoptosis during myocardial infarction." (PMID 34068550, 2021). "In our previous studies, we reported that FABP3 plays an important role in myocardial infarction and in-stent restenosis." (PMID 34458345, 2021). "FABP3 expression is elevated after myocardial injury, and is widely used as a marker of acute myocardial infarction and stroke." (PMID 27323829, 2016). "Serum concentration of FABP3 has been characterized as an early biochemical marker of acute myocardial infarction and a sensitive marker of ongoing myocardial damage in patients with heart failure." (PMID 25142635, 2014). "Serum concentration of FABP3 has been characterized as an early biochemical marker of acute myocardial infarction and a sensitive marker of myocardial damage in patients with heart failure." (PMID 24278421, 2013). "FABP-3 is currently used as a biomarker for identifying acute myocardial infarctions." (PMID 40278353, 2025). "Secondly, our findings regarding FABP3 align with the FAME-ER (Fatty Acid Binding Protein in Myocardial Infarction Evaluation in the Emergency Room) study, which reported an AUC of 0.73 for heart-type fatty acid-binding protein (H-FABP) ELISA in a cohort of 543 patients." (PMID 40363990, 2025). "Also known as the heart FABP (H‐FABP), the FABP‐3 is abundantly expressed in the myocardium and is released into circulation after a cardiac injury, such as myocardial infarction." (PMID 38269633, 2024). "The cardiac biomarker fatty acid-binding protein 3 (FABP3) has been used as a diagnostic tool for acute myocardial infarction (AMI) and non-ST-elevation myocardial infarction." (PMID 37255976, 2023). "Similarly, higher levels of serum FABP3 are observed in patients with ischemic stroke or myocardial infarction, and elevated levels of FABP7 are recorded in the serum of acute ischemic stroke patients." (PMID 36077044, 2022). "Since FABPs lack a secretory signal sequence, the presence of FABPs in serum has been considered to be a promising tissue-specific marker of tissue injury: FABP1 for liver damage, FABP2 for intestinal injury, and FABP3 for acute myocardial infarction and ongoing myocardial damage in heart failure." (PMID 24278421, 2013).
myocardial infarction (continued). "FABP‐3 is a small protein expressed in cardiomyocytes and renal distal tubular cells responsible for transporting long‐chain fatty acid, which would be released to the circulation during tissue injuries, such as myocardial infarction, heart failure, and renal tubule injury." (PMID 38269633, 2024). "In a mouse model for myocardial infarction (MI), it was demonstrated that ischemic conditions increased FABP3 expression under the regulation of hypoxia-inducible factor (HIF)-1α." (PMID 37207357, 2023). "Despite the functional complexity, FABP3 is currently utilized as a clinical biomarker for cardiac injury and heart failure, particularly in the diagnosis of myocardial infarction (MI)." (PMID 33105856, 2020).
heart failure (42 papers, 2011 to 2025). Inability of the heart to pump blood at an adequate rate to meet tissue metabolic requirements. "Inflammation is also a common factor between myocardial ischemia/heart failure and PADs, which are associated with increased circulatory FABP3 and thereby increased FABP3 exposure to endothelial cells." (PMID 36681124, 2023). "Cumulatively, these data suggest that the loss of FABP3 contributes to the progression of heart failure following TAC operation." (PMID 34458345, 2021). "FABP3 is superior to troponin as a highly sensitive marker of acute myocardial infarction and predictor of heart failure in patients with MS, which is strongly associated with psoriasis." (PMID 27864793, 2017). "Considering that FABP3 is a highly sensitive predictor of MI, especially in patients with MS, which is strongly linked to psoriasis, we assumed that this protein could serve as a marker of heart failure in patients with this dermatosis." (PMID 27864793, 2017). "We have demonstrated a beneficial value of FABP3 on cardiac hypertrophy and heart failure by inhibiting PPARα degradation." (PMID 34458345, 2021). "Collectively, this study for the first time demonstrates the indispensable role of FABP3 on metabolic homeostasis and the advance of hypertrophy and heart failure." (PMID 34458345, 2021). "Accordingly, the present study aimed to determine the metabolic effects of FABP3 on transverse aortic constriction (TAC)-induced cardiac hypertrophy and heart failure using genetic mutant Fabp3-null mice." (PMID 34458345, 2021). "It has been reported that the FABP3-PPARα axis has an indispensable role in Ang II-induced cardiac hypertrophy and heart failure." (PMID 34944635, 2021). "The patients with the highest FABP‐3 levels were the oldest (p < .001), having the highest systolic BP (p = .007), lowest diastolic BP (p = .047), highest rates of hypertension (p < .001), DM (p < .001), and heart failure (p < .001)." (PMID 38269633, 2024). "FABP3: fatty acid binding protein 3; FABP4: fatty acid binding protein 4; HF: heart failure; NYHA: New York heart association; LVEF: left ventricular ejection fraction; NTproBNP: pro-B-type natriuretic peptide; eGFR estimated glomerular filtration rate (CKD-EPI equation)." (PMID 36978893, 2023). "Some explanations of this phenomenon might be focused on fatty acid mobilization, since a high expression levels of the fatty transporter, fatty acid binding protein 3 (FABP3), was detected in epicardial fat from patients with heart failure, or on dysfunction for glucose uptake." (PMID 32290181, 2020). "The expressions of ACADM, FABP3, ECH1, ACAA2, EHHADH and CPT1A in the left atria were significantly up-regulated in the MR patients with heart failure compared to patients with aortic valve disease and heart failure and normal controls." (PMID 27250500, 2016). "Taken together, these observations confirm that FABP3 defect contributes to compromised FAO and ATP production; on the other hand, it exacerbates glycolysis and toxic lipid accumulation, both of which ultimately aggravate metabolic derangement and heart failure." (PMID 34458345, 2021). "Indeed, marked elevation of heart failure markers such as brain natriuretic peptide (BNP), fatty acid-binding protein 3 (FABP3), and creatine kinase (CK) in SMA patients suggests that normal cardiac function may require sufficient functional expression of SMN." (PMID 32384912, 2020).
acute coronary syndrome (39 papers, 2010 to 2025). Signs and symptoms related to acute ischemia of the myocardium secondary to coronary artery disease. "FABP3 elevations have also been related to different cardiac pathologies, including several cardiomyopathies, acute coronary syndrome (ACS) and HF and proposed as a silent biomarker for the progression of myocardial damage in subjects with insulin resistance." (PMID 36978893, 2023). "Because of the cytosolic location, FABP3 is rapidly released into the circulation following cardiac injury and has been regarded as an early sensitive biomarker of acute coronary syndrome." (PMID 25505575, 2014). "FABP3 levels are elevated in toxic or drug-induced skeletal muscle injuries in all forms of HF, including HF with preserved ejection fraction, in various cardiomyopathies, and in acute coronary syndrome, and it is a useful marker for ongoing myocardial damage." (PMID 39795963, 2024). "The role of FABP3 and FABP4 as independent predictors of mortality has been reported in subjects with pulmonary embolism and after acute coronary syndrome (ACS), and all-cause death increased together with increasing FABP3 tertiles in subjects with stable angina." (PMID 36978893, 2023). "FABP3 has been shown to be able to reliably diagnose AMI soon after symptom onset, and also to confirm or exclude the diagnoses of acute coronary syndromes." (PMID 37255976, 2023).
myocardial ischemia (30 papers, 2008 to 2025). A disorder of cardiac function caused by insufficient blood flow to the muscle tissue of the heart. "FABP3 has also been examined as a diagnostic indicator for myocardial ischemia in situations without overt necrosis." (PMID 25505575, 2014).
ischemia (27 papers, 2008 to 2026). A hypoperfusion of the BLOOD through an organ or tissue caused by a PATHOLOGIC CONSTRICTION or obstruction of its BLOOD VESSELS, or an absence of BLOOD CIRCULATION. "Specifically, Troponin I is considered related to necrosis, FABP3 to ischemia, and NT-proBNP and BNP to hemodynamic changes." (PMID 38030645, 2023). "In a clinical scenario, FABP3 released into the circulation following ischemia may help by a vasodilatory effect to increase the blood flow to the impacted tissues." (PMID 36681124, 2023). "AA is known to elevate in during ischemia and it is also a strong ligand of FABP3 and FABP5." (PMID 34068550, 2021). "Moreover, co-staining FABPs in different cell types in the cortical area of the penumbra suggests that increased FABP3, FABP5 and FABP7 expression occurred only in specific cells expressing these proteins before ischemia." (PMID 34068550, 2021). "However, it is unclear whether one FABP or FABP3, FABP5 and FABP7 collectively induced mPGES-1 after ischemia." (PMID 34068550, 2021). "Fatty acid binding protein 3 (FABP3) is an intracellular protein that is normally absent from plasma but becomes released into circulation and excreted into urine following skeletal muscle injury, which may occur due to ischemia from PAD." (PMID 35795372, 2022).
diabetes (25 papers, 2011 to 2026). "Higher FABP4 has been linked to metabolic diseases such as obesity and diabetes and higher FABP3 in the plasma has been linked to fatigue, physical activity intolerance, and muscle atrophy." (PMID 37697678, 2023). "Moreover, positive associations between FABP4 with body mass index, diabetes mellitus, hypertension, systolic blood pressure, low-density lipoprotein-cholesterol, triglycerides, creatinine, and FABP3 were found." (PMID 37255976, 2023). "Moreover, with increasing FABP3 levels, the patients had higher rates of hypertension, diabetes mellitus, abnormal QTc interval, LVSD, and all-cause mortality, and higher levels of hs-CRP, WBC count, and visfatin." (PMID 33850478, 2021). "The aim of this study was therefore to evaluate the plasma levels of FABP3 at different stages of estimated glomerular filtration rate (eGFR) in patients with type 2 diabetes mellitus (T2DM)." (PMID 34975301, 2022). "Furthermore, a sex and age-adjusted multiple linear regression model revealed a positive association between FABP4 with BMI, diabetes mellitus, hypertension, SBP, LDL-C, triglycerides, creatinine, and FABP3." (PMID 37255976, 2023). "Furthermore, FABP4 was positively associated with age, BMI, diabetes mellitus, hypertension, hyperlipidemia, SBP, LDL-C, triglycerides, creatinine, and FABP3." (PMID 37255976, 2023). "Additionally, other four genes (FCGR1A, NCF2, MYOC, and FABP3) (in bold) were also enriched in these OP- and diabetes-related biological processes and pathways, comparing to the target genes in the TF network." (PMID 36050744, 2022). "Furthermore, FABP3 levels were found to be significantly increased in the urine of patients with diabetes prior to the occurrence of microalbuminuria." (PMID 36387916, 2022). "Furthermore, the high FABP3 group were older (p < 0.0001) and had higher prevalence rates of hypertension (p = 0.007), diabetes mellitus (p < 0.0001), abnormal QTc interval (p < 0.0001), LVSD (p = 0.043), and all-cause mortality (p < 0.0001)." (PMID 33850478, 2021). "The patients with G3a-G4 had higher cardiovascular disease, oral hypoglycemic agent rates (OHA), age, diabetes duration, uric acid, estimated GFR, UACR, FABP1, and FABP3 than those with G1 and G2." (PMID 34975301, 2022). "As previously reported, urinary FABP3 concentration was significantly elevated in normoalbuminuric diabetes patients compared to nondiabetic control subjects who had a similar eGFR." (PMID 34975301, 2022). "Moreover, we found positive associations between plasma FABP4 with BMI, diabetes mellitus, hypertension, SBP, LDL-C, triglycerides, creatinine, and FABP3, and negative associations between plasma FABP4 with HDL-C, eGFR, and HF HRV." (PMID 37255976, 2023). "Conversely, four biomarkers showed higher serum levels in those without diabetes (CT-1, LDH-B, FABP-3, and myoglobin)." (PMID 39772209, 2024).